OR2T8 (olfactory receptor family 2 subfamily T member 8)
Description:
Odorant receptor.
Synonyms: OR2T8P
Tractability: Antibody: UniProt places it where antibodies can reach, with medium confidence; UniProt predicts a signal peptide or a membrane-spanning region; its Gene Ontology location is reachable by antibodies, with medium confidence.
Gene: Protein-coding gene on chromosome 1 (247,920,252 to 247,923,152, forward strand). Ensembl gene ENSG00000177462.
Subcellular location: Cell membrane
Pathways (Reactome):
Sensory Perception: Expression and translocation of olfactory receptors
Gene Ontology:
Molecular function: olfactory receptor activity; G protein-coupled receptor activity
Biological process: detection of chemical stimulus involved in sensory perception of smell; G protein-coupled receptor signaling pathway
Cellular component: plasma membrane; membrane
Genetic constraint (gnomAD): Loss-of-function variants: 1 observed, 0.34 expected, observed/expected ratio (o/e) 2.92. That is too few expected variants to judge how well the gene tolerates losing a copy. Missense variants: 123 observed, 190.81 expected, observed/expected ratio (o/e) 0.64, 90% interval 0.56 to 0.75. Synonymous variants: 45 observed, 72.52 expected, observed/expected ratio (o/e) 0.62, 90% interval 0.49 to 0.8.
Homologues: Orthologues: dog OR2T15 (77% identical), dog OR2T13 (77% identical), dog OR2T20 (77% identical), dog OR2T24 (76% identical), mouse Or2t44 (74% identical), rat Olr1454 (73% identical), rat Or2t44 (72% identical), rat Or2t44b (72% identical). Paralogues in human: OR2T33 (94% identical), OR2T12 (90% identical), OR2M2 (57% identical), OR2M3 (57% identical), OR2M5 (55% identical), OR2M7 (55% identical), OR2M4 (55% identical), OR2V1 (54% identical), OR2V2 (54% identical), OR2T27 (54% identical), OR2T2 (54% identical), OR2T35 (54% identical), and 80 more.
Diseases named in the same sentence as OR2T8 in open-access papers:
OR2T8 is named in the same sentence as 1 disease in open-access papers, as found by Europe PMC text mining. Sharing a sentence is not in itself a finding about the gene and the disease.
OR2T8 shares sentences with these, for which no sentence is quoted: breast carcinoma (1 paper).